BMP8A (bone morphogenetic protein 8a)
Description:
Induces cartilage and bone formation. May be the osteoinductive factor responsible for the phenomenon of epithelial osteogenesis. Plays a role in calcium regulation and bone homeostasis (By similarity). Signaling protein involved in regulation of thermogenesis and energy balance. Proposed to increase the peripheral response of brown adipose tissue (BAT) to adrenergic stimulation while acting centrally in the hypothalamus to increase sympathetic output to BAT. Growth factor of the TGF-beta superfamily that plays important role in various biological processes, including spermatogenesis, osteogenesis, steroidogenesis as well as regulation of energy balance. Initiates the canonical BMP signaling cascade by associating with type I receptor BMPR1A and type II receptor BMPR2. Once all three components are bound together in a complex at the cell surface, BMPR2 phosphorylates and activates BMPR1A. In turn, BMPR1A propagates signal by phosphorylating SMAD1/5/8 that travel to the nucleus and act as activators and repressors of transcription of target genes. In addition, activates the SMAD2/3 pathway.
Synonyms: OP-2; Op2
Tractability: Antibody: UniProt places it where antibodies can reach, with high confidence; UniProt predicts a signal peptide or a membrane-spanning region; its Gene Ontology location is reachable by antibodies, with medium confidence. PROTAC: ubiquitination databases record sites on it.
Gene: Protein-coding gene on chromosome 1 (39,491,069 to 39,529,869, forward strand). Ensembl gene ENSG00000183682.
Subcellular location: Secreted
Subcellular location (Human Protein Atlas): Vesicles; Predicted to be secreted
Gene Ontology:
Molecular function: cytokine activity; growth factor activity
Biological process: cell differentiation; diet induced thermogenesis; energy homeostasis; negative regulation of insulin secretion; BMP signaling pathway; developmental process
Cellular component: extracellular region
Genetic constraint (gnomAD): Loss-of-function variants: 11 observed, 13.61 expected, observed/expected ratio (o/e) 0.81, 90% interval 0.51 to 1.34. The upper end of that interval is the gene's LOEUF score, 1.34, which puts it in group 5 of 6, group 1 being the genes least tolerant of losing a copy. Missense variants: 176 observed, 188.65 expected, observed/expected ratio (o/e) 0.93, 90% interval 0.82 to 1.06. Synonymous variants: 67 observed, 72.18 expected, observed/expected ratio (o/e) 0.93, 90% interval 0.76 to 1.14.
Homologues: Orthologues: macaque BMP8B (95% identical), tropical clawed frog bmp8 (64% identical), zebrafish bmp8a (55% identical). Paralogues in human: BMP8B (98% identical), BMP6 (52% identical), BMP5 (52% identical), BMP7 (52% identical), BMP2 (29% identical), GDF2 (28% identical), GDF6 (28% identical), BMP4 (27% identical), GDF7 (25% identical), BMP10 (25% identical), GDF5 (24% identical), NODAL (22% identical), and 19 more.
Diseases named in the same sentence as BMP8A in open-access papers:
BMP8A is named in the same sentence as 26 diseases in open-access papers, as found by Europe PMC text mining. Sharing a sentence is not in itself a finding about the gene and the disease. The quoted sentences say what the papers report.
breast carcinoma (3 papers, 2023 to 2024). "A previous study revealed that high BMP8A expression was associated with poorer overall survival (OS) in breast cancer." (PMID 39100096, 2024). "Since BMP8A played a pivotal role in the progression of breast cancer, and breast cancer is well known as a disease prone to bone metastasis, the role of BMP8A in the bone metastasis of BC was explored in the current study." (PMID 39100096, 2024). "Clinical relevance of deregulated BMP8A in breast cancer was assessed using Kaplan-Meier online analysis." (PMID 39100096, 2024). "Studies have established a strong correlation between BMP8A expression and prognosis in renal cell carcinoma and breast cancer, where high BMP8A expression typically signals a poorer prognosis." (PMID 38671425, 2024). "In summary, a shift in the expression pattern of BMPs in breast cancer, including increased BMP8A, BMPR1B and decreased BMP6, BMP7, ACVR1C, TGFBR2, TGFBR3 and BMPR2 presented a subtype specific role." (PMID 37333824, 2023). "However, this still needs to be fully investigated to elucidate the exact role of BMP8A in the spread of breast cancer cells to the bone and their subsequent colonization." (PMID 39100096, 2024). "Aberrant expression of BMP8A in breast cancer was first determined by analyzing The Cancer Genome Atlas breast cancer cohort (TCGA-BRCA) and an immunohistochemical (IHC) staining of BMP8A in a breast cancer tissue microarray (TMA)." (PMID 39100096, 2024). "In breast cancer, high EGFR expression is found in TNBC subtype, however, analysis of the TCGA-BRCA cohort reveals that BMP8A expression is lower in TNBC compared to the other three subtypes." (PMID 39100096, 2024). "In four main subtypes of breast cancer, elevated expression of BMPR1B and ACVR2B were seen in Luminal A subtype, while BMP4, GDF15 and ACVR1B were higher in Luminal B, TGFBR1 and BMP8A were higher in HER2 positive, BMP2, BMP6 and GDF5 were higher in TNBC." (PMID 37333824, 2023).
renal cell carcinoma (3 papers, 2023 to 2024). "Among the 5 necroptosis-related genes included in the prognostic signature, patients with renal cell carcinomas had high levels of BMP8A expression, which promoted survival and drug resistance." (PMID 36910333, 2023).
thyroid cancer (3 papers, 2021 to 2024). "Additionally, by combining DNA methylation with gene expression data, we further found a relationship between the expression and methylation level in some genes, such as RAP1GAP and BMP8A, which proved to play a role in the progression of thyroid cancer." (PMID 36612238, 2022). "For instance, we failed to explore the role of the 5 feature genes (BMP8A, ADARB2, SALL3, PPBP, and SCN1A) in onset and progression of thyroid carcinoma by molecular experiments, cell experiments, or animal experiments." (PMID 34697553, 2021).
fibrosis (2 papers, 2023 to 2025). the formation of excess fibrous connective tissue in an organ or tissue in a reparative or reactive process. "Accordingly, on the univariate logistic regression analysis, serum BMP8A levels were significantly associated with advanced fibrosis with a good accuracy to identify NASH patients with F3-F4 stages (AUROC, 0.742)." (PMID 37106416, 2023). "In fact, the AUROC of circulating BMP8A concentrations to identify patients with advanced fibrosis (F3-F4) was 0.74 (p˂0.0001)." (PMID 37106416, 2023). "The AUROC of circulating BMP8A concentrations to identify patients with advanced fibrosis (F3-F4) was 0.74 (CI 95% (0.63–0.85); p ˂ 0.0001)." (PMID 37106416, 2023). "Serum BMP8A was measured in 302 patients with biopsy-proven MASH: 171 with non- or mild fibrosis (F0-F2) and 131 with advanced fibrosis (F3-F4) recruited from seven university hospitals located in different cities in Spain." (PMID 41257923, 2025). "Taking this into account, we measured BMP8A in serum from NASH patients with or without advanced fibrosis as well as in individuals with histologically normal liver (NL)." (PMID 37106416, 2023). "In order to determine whether elevated BMP8A expression observed in the liver of BDL mice was due to the fibrogenic process and not to the cholestasic liver injury induced by BDL, we determined its hepatic expression profile in other experimental fibrosis models." (PMID 37106416, 2023). "Furthermore, serum BMP8A was measured in mice with bile duct ligation (BDL), in 36 subjects with histologically normal liver (NL) and in 85 patients with biopsy-proven non-alcoholic steatohepatitis (NASH): 52 with non- or mild fibrosis (F0-F2) and 33 with advanced fibrosis (F3-F4)." (PMID 37106416, 2023).
Granuloma (2 papers, 2013). A compact, organized collection of mature mononuclear phagocytes, which may be but is not necessarily accompanied by accessory features such as necrosis. "Interestingly, lack of BMP8a and BMP7 expression in Bmp8a−/− and Bmp8a/Bmp7−/− mice provoked inflammatory situations in the caput epididymides of these animals characterized by the occurrence of sperm-mediated granulomas." (PMID 23840489, 2013).
liver fibrosis (2 papers, 2023 to 2025). "Serum BMP8A levels were higher in BDL mice compared to control animals, and a statistically significant association was found between serum BMP8A levels and its hepatic expression pattern and with the hepatic fibrosis stage as well." (PMID 37106416, 2023). "This study provides experimental and clinical evidence indicating that BMP8A is a novel molecular target linked to liver fibrosis and introduces an efficient algorithm based on serum BMP8A levels to screen patients at risk for advanced hepatic fibrosis." (PMID 37106416, 2023). "We recently developed a non-invasive algorithm termed BMP8A Fibrosis Score (BFS) which is able to identify MASH patients with advanced liver fibrosis." (PMID 41257923, 2025). "It is noteworthy to highlight that this is the first study measuring serum BMP8A concentrations in patients with liver fibrosis." (PMID 37106416, 2023). "In this study, we assessed the potential role of bone morphogenetic protein 8A (BMP8A) as a novel target involved in liver fibrosis progression." (PMID 37106416, 2023). "Histological assessment and BMP8A expression were determined in different murine models of hepatic fibrosis." (PMID 37106416, 2023). "However, our preclinical studies showed that BMP8A expression was upregulated in different experimental models of liver fibrosis." (PMID 37106416, 2023). "Finally, in order to evaluate the usefulness of serum BMP8A for predicting advanced liver fibrosis (F3-F4) in NAFLD patients, the area under the ROC curve (AUROC) was analyzed in the entire study population." (PMID 37106416, 2023). "In the present study we provide data revealing, for the first time, that hepatic Bmp8a expression is upregulated in distinct preclinical models of liver fibrosis and positively correlated with the stage of liver fibrosis, as well as with the hepatic mRNA levels of different markers of fibrogenesis." (PMID 37106416, 2023). "Of relevance, our findings herein suggest that BMP8A could be an important mediator of liver fibrosis progression, regardless the etiology of chronic liver damage; however, further experimental studies are needed to elucidate the precise role of BMP8A in the pathophysiology of liver fibrogenesis." (PMID 37106416, 2023). "Another relevant finding to point out in the present study is that serum BMP8A levels are significantly associated with the hepatic fibrosis stage of the NASH patients studied, indicating that circulating BMP8A may be a useful biomarker to distinguish advanced hepatic fibrosis from mild fibrosis." (PMID 37106416, 2023). "Firstly, to determine BMP8A expression during liver fibrosis, we established a BDL-induced liver fibrosis model in mice." (PMID 37106416, 2023).
brachydactyly (1 paper, 2025). A disease characterized by the presence of brachydactyly, including syndromic and non-syndromic forms. "Functional protein association network analysis demonstrates a strong association of BMP8A and FGFR1 with other brachydactyly disease‐causing genes." (PMID 41036481, 2025).
epilepsy (1 paper, 2020). A brain disorder characterized by episodes of abnormally increased neuronal discharge resulting in transient episodes of sensory or motor neurological dysfunction, or psychic dysfunction. "The loci near BMP8A and PTPRK initially showed evidence for pleiotropy, because of their nominal significant association in both ALS and epilepsy GWAS and stronger statistical association in the meta-analysis and sign-independent meta-analysis, respectively." (PMID 32409253, 2020).
Hepatic steatosis (1 paper, 2023). Steatosis is a term used to denote lipid accumulation within hepatocytes. "Taken together, HFD-induced obesity and hepatic steatosis are more severe in bmp8a-/- zebrafish than WT zebrafish." (PMID 37553521, 2023).
Obesity (1 paper, 2023). Accumulation of substantial excess body fat. "In this study, we found that compared to WT, bmp8a-/- zebrafish exhibited higher body weight and increased fat production, confirming the linking of Bmp8a with obesity." (PMID 37553521, 2023). "Collectively, our findings indicate that Bmp8a plays a critical role in regulating lipid metabolism and adipogenesis, potentially providing a therapeutic approach for obesity and its comorbidities." (PMID 37553521, 2023). "In conclusion, we reported that bmp8a-/- zebrafish displayed obesity and fatty liver by decreasing fatty acid oxidation via downregulation of the phosphorylation of AMPK and ACC." (PMID 37553521, 2023). "Here, we report that bmp8a-/- zebrafish display obesity and fatty liver." (PMID 37553521, 2023). "Thus, Bmp8a appears to regulate obesity through multiple molecular pathways." (PMID 37553521, 2023). "Therefore, it is conceivable that obesity could result if the inhibitory regulation of adipogenesis by Bmp8a is disrupted, which is consistent with our findings of significantly increased body weight in bmp8a-/- zebrafish." (PMID 37553521, 2023).
osteosarcoma (1 paper, 2023). A usually aggressive malignant bone-forming mesenchymal neoplasm, predominantly affecting adolescents and young adults. "A recent study showed that BMP8A can diminish chemotherapy sensitivity in ccRCC by promoting Nrf2 phosphorylation and activating TRIM24, implying its potential role in drug resistance in osteosarcoma." (PMID 37964984, 2023).
papillary thyroid carcinoma (1 paper, 2024). "We validated the relationship between BMP8A expression and recurrence risk stratification in patients with papillary thyroid carcinoma (PTC) by integrating other clinicopathological indicators." (PMID 38671425, 2024). "In our study, we identified three genes associated with SUMOylation modification—BMP8A, RGS8, and SERPIND1—as significant to the prognosis of papillary thyroid carcinoma (PTC) patients." (PMID 38671425, 2024). "Given the critical role of immune factors in the progression of papillary thyroid carcinoma (PTC), our study aimed to elucidate the correlations between BMP8A, RGS8, and SERPIND1 and immune cell infiltration." (PMID 38671425, 2024). "Similar to BMP8A, there are no comprehensive studies yet that explore the relationship between RGS8 expression and the prognosis of papillary thyroid carcinoma, indicating an area ripe for further research." (PMID 38671425, 2024).
polycystic ovary syndrome (1 paper, 2022). A disorder that manifests as multiple cysts on the ovaries. "Previous studies have shown that several BMPs, including BMP2, BMP4, BMP5, BMP6, BMP7 and BMP8A are expressed in the granulosa cells from normally cycling and polycystic ovary syndrome women." (PMID 35395768, 2022).
viral infection (1 paper, 2021). "We demonstrated that Bmp8a was a previously unrecognized regulator functioning in antiviral immune responses of zebrafish Danio rerio, providing a target for control of viral infection." (PMID 33750893, 2021). "Our study uncovers a previously unrecognized role of Bmp8a in regulation of antiviral immune responses and provides a target for controlling viral infection." (PMID 33750893, 2021). "Next, we measured the expression of bmp8a in ZFL cells upon virus infection." (PMID 33750893, 2021). "Upon virus infection, the expression of bmp8a is activated by Stat1a/Stat1b directly." (PMID 33750893, 2021). "We also show for the first time that Bmp8a interacts with Alk6a, which promotes the phosphorylation of Tbk1 and Irf3 through p38 MAPK pathway, and induces the production of type I interferons (IFNs) in response to viral infection." (PMID 33750893, 2021).
tumor (7 papers, 2014 to 2024). "We discovered that the expression of BMP8A in the tumor tissues of patients in the intermediate-high-risk group was significantly higher than that in the low-risk group." (PMID 38671425, 2024). "Since the mortality rate of PTC patients is quite low, our primary evaluation focused on the relationship between BMP8A expression and tumor recurrence in PTC patients." (PMID 38671425, 2024). "In our final step, we conducted immunohistochemical staining on tumor samples from PTC patients at our center and integrated this with their clinical data to validate BMP8A’s effectiveness in predicting recurrence in PTC." (PMID 38671425, 2024). "Among 11 BMPs, BMP3 and BMP8A expression levels were upregulated, and 5 BMPs (BMP2, BMP5, GDF5, BMP6, and GDF10) downregulated in tumor tissues compared with normal tissues." (PMID 34745928, 2021). "BMP8A and TGFBR1 were highly correlated with HER2 in the HER2 positive tumours." (PMID 37333824, 2023). "The probability of interaction between tumor cells and fibroblast receptor-ligand pairs was higher than that of thyroid cells, especially in TGFB1/ACVR1/TGFBR1, FGF18/FGFR1, BTC/EGFR, BMP8A/BMPR1A/BMPR2, and BMP8A/BMPR1A/BMPR2." (PMID 37733241, 2023). "However, we cannot preclude additional paracrine factors also contributing to tumor formation since transcripts for other secreted growth regulators (SOST, BMP7, BMP8A, WNT5B, WNT10B, and FGF21) exhibited increased abundance in SHP2-depleted pellet cultures." (PMID 24875294, 2014). "Therefore, it can be inferred that downregulation of BMP8A, RGS8, and SERPIND1 might lead to a shift in the immune microenvironment towards a pro-tumor state, thus facilitating the occurrence and advancement of PTC." (PMID 38671425, 2024).
cancer (2 papers, 2021 to 2024). A tumor composed of atypical neoplastic, often pleomorphic cells that invade other tissues. "BMP8A staining was mainly distributed in the cytoplasm, some staining was seen in the cell nuclei, and some staining was also observed in carcinoma stroma such as fibrocytes and immune cells." (PMID 39100096, 2024). "Skewed genes include a number of additional factors with established roles in cancer (e.g., BMP8A and BUB1), as well as others." (PMID 34944895, 2021).
infection (1 paper, 2021). The state of being infected such as from the introduction of a foreign agent such as serum, vaccine, antigenic substance or organism. "This indicated that the expression of bmp8a was inducible by infection with virus or its mimic poly(I:C)." (PMID 33750893, 2021). "We also detected the expression of bmp8a upon infection with GCRV or poly(I:C) in vivo." (PMID 33750893, 2021). "Moreover, EPC cells cotransfected with bmp8a expressing plasmid and IFNφ1, IFNφ3, or EPC IFN promoter-driven luciferase plasmid, followed by infection with or without GCRV, had markedly increased intracellular IFNφ1, IFNφ3, or EPC IFN promoter-driven luciferase activities." (PMID 33750893, 2021).
BMP8A also shares sentences with these, for which no sentence is quoted: breast tumours (1 paper); diabetes (1); hypogonadism (1); liver diseases (1); non-alcoholic steatohepatitis (1); osteoarthritis (1); triple-negative breast carcinoma (1); type 2 diabetes (1); urothelial carcinoma (1).